PAICS (phosphoribosylaminoimidazole carboxylase and phosphoribosylaminoimidazolesuccinocarboxamide synthase)
Description:
Bifunctional phosphoribosylaminoimidazole carboxylase and phosphoribosylaminoimidazole succinocarboxamide synthetase catalyzing two reactions of the de novo purine biosynthetic pathway.
Synonyms: AIRC; ADE2; PAIS; ADE2H1; PAICSD
Tractability: Small molecule: a structure with a bound ligand is known; a high-quality ligand is known. PROTAC: ubiquitination databases record sites on it; its protein half-life has been measured; a small molecule that binds it is known.
Target class: Enzyme
Gene: Protein-coding gene on chromosome 4 (56,435,058 to 56,464,578, forward strand). Ensembl gene ENSG00000128050.
Subcellular location (Human Protein Atlas): Cytosol
Pathways (Reactome):
Metabolism: Purine ribonucleoside monophosphate biosynthesis
Gene Ontology:
Molecular function: cadherin binding; identical protein binding; phosphoribosylaminoimidazole carboxylase activity; phosphoribosylaminoimidazolesuccinocarboxamide synthase activity; protein binding
Biological process: 'de novo' AMP biosynthetic process; 'de novo' IMP biosynthetic process; 'de novo' XMP biosynthetic process; GMP biosynthetic process; purine nucleobase biosynthetic process; purine nucleotide biosynthetic process
Cellular component: cytoplasm; extracellular exosome; membrane; cytosol
Genetic constraint (gnomAD): Loss-of-function variants: 6 observed, 15.34 expected, observed/expected ratio (o/e) 0.39, 90% interval 0.21 to 0.77. The upper end of that interval is the gene's LOEUF score, 0.77, which puts it in group 3 of 6, group 1 being the genes least tolerant of losing a copy. Missense variants: 199 observed, 216.26 expected, observed/expected ratio (o/e) 0.92, 90% interval 0.82 to 1.03. Synonymous variants: 73 observed, 76.45 expected, observed/expected ratio (o/e) 0.95, 90% interval 0.79 to 1.16.
Homologues: Orthologues: chimpanzee PAICS (99% identical), macaque PAICS (97% identical), guinea pig Paics (97% identical), rat Paics (96% identical), mouse Paics (95% identical), rabbit PAICS (94% identical), pig PAICS (92% identical), dog PAICS (92% identical), zebrafish paics (79% identical), Drosophila melanogaster Paics (59% identical), tropical clawed frog paics (51% identical), Caenorhabditis elegans paic-1 (50% identical).
Diseases named in the same sentence as PAICS in open-access papers:
PAICS is named in the same sentence as 60 diseases in open-access papers, as found by Europe PMC text mining. Sharing a sentence is not in itself a finding about the gene and the disease. The quoted sentences say what the papers report.
breast carcinoma (16 papers, 2017 to 2025). "Furthermore, we validated the underlying mechanism of the miR-4731-5p/PAICS/p-FAK axis in breast cancer." (PMID 35379785, 2022). "In the present study, we primarily identified that the PAICS gene, which encodes an enzyme required for de novo purine biosynthesis, might be a potential tumor marker in human breast cancer." (PMID 30097015, 2018). "One of the top hits encodes the enzyme PAICS whose role in breast cancer was largely unknown." (PMID 37172090, 2023). "PAICS is overexpressed in glioma, breast cancer, pancreatic cancer, gastric cancer, prostate cancer, bladder cancer, and colorectal cancer, and its high expression is closely related to the poor survival of tumor patients." (PMID 38463398, 2024). "Here, we report the discovery of an important correlation of PAICS levels with tumor progression, estrogen-independent cell proliferation, and tamoxifen resistance of ERα+ breast cancer." (PMID 37172090, 2023). "NOLC1, PAICS, and TEX10 expression are associated with cancer stemness, poor prognosis, and resistance to interventional chemo/radiotherapy in patients with breast cancer, esophageal cancer, hepatocellular carcinoma or melanoma." (PMID 37435077, 2023). "In line with this, survival analyses of patients with ERα+ and ERα− breast cancer revealed a statistically significant correlation between the expression levels of PAICS and poor outcome in ERα+ breast cancer including those that were treated with tamoxifen." (PMID 37172090, 2023). "In breast cancer, targeting PAICS was shown to reduce the proliferation of breast cancer cells by inducing a cell cycle arrest." (PMID 37172090, 2023). "Next, we used the Kaplan-Meier plotter to search for the correlation between PAICS mRNA expression levels and survival of patients with breast cancer." (PMID 37172090, 2023). "Last, our results showed that targeting PAICS either with gene editing or with the specific small-molecule inhibitor MRT can sensitize breast cancer cells to 4-OHT." (PMID 37172090, 2023). "The specific correlation between PAICS expression and breast cancer was further investigated using a human breast tissue microarray (TMA)." (PMID 37172090, 2023). "Similar elevations in PAICS expressions were observed in breast cancer cells, wherein MCF-7 and MDA-MB-231 cells exhibited the most profound upregulation, and thus were selected for further experimentation." (PMID 35379785, 2022). "We also documented similar expression trends concerning the expression of p-FAK and PAICS in the breast cancer lung metastasis model as in the nude mouse model of breast cancer xenograft tumor by immunohistochemistry." (PMID 35379785, 2022). "The expression of proteins involved in cell cycle regulation and apoptosis differs in PAICS KD breast cancer cells." (PMID 36557247, 2022). "Herein, the results of RT-PCR and western blot assay illustrated that PAICS expression levels were enhanced in breast cancer tissues." (PMID 35379785, 2022). "To further elaborate on the role of PAICS in breast cancer, we first established a PAICS silencing cell line." (PMID 35379785, 2022). "PAICS, a de novo purine metabolic enzyme, is significantly overexpressed in several tumor types, including lung adenocarcinoma, breast cancer, diffuse large B-cell lymphoma, and prostate cancer." (PMID 35664305, 2022). "Significant proteolytic cleavage of PARP was detected in ZR-75-30 breast cancer cells infected with siPAICS by western blotting, indicating an anti-apoptotic role for PAICS." (PMID 30097015, 2018). "Further investigation is required to reveal the molecular exact basis for the oncogenic function of PAICS in breast cancer cells." (PMID 30097015, 2018). "This study aimed to evaluate the role of PAICS in human breast cancer, which remains the most frequently diagnosed cancer and the leading cause of cancer-related death among women in less developed countries." (PMID 30097015, 2018).
breast carcinoma (continued). "Knockdown of endogenous PAICS expression by shRNA-expressing lentivirus significantly decreased the viability and proliferation of ZR-75-30 breast cancer cells." (PMID 30097015, 2018). "Depletion of PAICS largely cancelled breast cancer expansion, exemplifying a prognostic gene with breast cancer activity." (PMID 28411283, 2017). "In breast cancer, phosphoribosylaminoimidazole carboxylase and phosphoribosylaminoimidazolesuccinocarboxamide synthase (PAICS), a bifunctional enzyme in DNPS, modulates the activity of estrogen receptor α (Erα) and confers tamoxifen resistance upon breast cancer cells." (PMID 40097378, 2025). "We constructed a risk model based on the expression levels of these RBPs and found that ADAT2, C2orf15, SRP72, PAICS, RBMS3, APOBEC3G, NOA1, and ACO1 could be used for risk assessment in terms of breast cancer prognosis." (PMID 38783078, 2024). "Next, we determined more specifically whether the differential expression of PAICS affects the proliferation rate of ERα+ breast cancer cells." (PMID 37172090, 2023). "From a therapeutic perspective, we propose that PAICS may be a promising drug target to overcome tamoxifen resistance of ERα+ breast cancer." (PMID 37172090, 2023). "Hence, PAICS expression levels are directly correlated with resistance of ERα+ breast cancer cells to 4-OHT treatment." (PMID 37172090, 2023). "Therefore, we propose that the impact of cAMP/PKA signaling on ERα activity explains how PAICS levels can be linked to estrogen-independent and 4-OHT–resistant proliferation of ERα+ breast cancer cells." (PMID 37172090, 2023). "Furthermore, the connection between PAICS and endocrine resistance needs to be further strengthened in the future with cohort studies in patients with breast cancer." (PMID 37172090, 2023). "Moreover, PAICS was also significantly highly expressed in breast cancer tissue samples included in the TCGA and GTEx databases." (PMID 35379785, 2022). "Herein, we unfolded that overexpression of PAICS could promote cell glycolysis and induced EMT by phosphorylating FAK, which could potentially serve as the mechanism contributing to breast cancer progression due to loss of miR-4731-5p." (PMID 35379785, 2022). "PAICS was previously reported to promote the malignant progression of breast cancer." (PMID 35379785, 2022). "Additionally, overexpression of PAICS led to an enhancement in the migration and invasion of breast cancer cells, whereas miR-4731-5p mimic treatment led to the opposing trends." (PMID 35379785, 2022). "Moreover, miR-4731-5p exerted an inhibitory effect on glycolysis, EMT, migration, and invasion in breast cancer cells via regulation of PAICS-dependent phosphorylation of FAK." (PMID 35379785, 2022). "Furthermore, PAICS knockdown (KD) in breast cancer cell lines and lung adenocarcinoma cells resulted in reduced cell viability and proliferation, and cell cycle disruption." (PMID 36557247, 2022). "miR-4731-5p was poorly expressed and PAICS was highly expressed in breast cancer tissues and cells." (PMID 35379785, 2022). "Altogether, these findings highlight the involvement of miR-4731-5p and PAICS in breast cancer." (PMID 35379785, 2022). "Therefore, we can conclude that the growth inhibitory effect of PAICS silencing in breast cancer cells was probably due to the induction of mitochondrial-related apoptosis." (PMID 30097015, 2018). "Our findings demonstrate for the first time that PAICS plays an essential role in breast cancer cell growth, which might be useful for the identification of novel targets for human breast cancer therapy." (PMID 30097015, 2018). "Therefore, it is likely that PAICS can modulate breast cancer growth via the regulation of a subset of cancer-related genes involved in G1-S checkpoint progression." (PMID 30097015, 2018).
breast carcinoma (continued). "We propose that pharmacological inhibition of components within this network, such as PAICS, may be used in conjunction with the Fra-1 prognostic classifier towards personalized management of poor prognosis breast cancer." (PMID 28411283, 2017). "Together, these results indicate that increased PAICS expression may stimulate the proliferation and migration of ERα+ breast cancer cells in the absence of estrogen, whereas PAICS deficiency restricts cell proliferation to the presence of estrogen." (PMID 37172090, 2023). "Moreover, downregulation of PAICS brought about inhibited EMT in breast cancer." (PMID 35379785, 2022). "Overall, these findings indicated PAICS could promote FAK phosphorylation in breast cancer cells." (PMID 35379785, 2022). "Whether inhibition of de novo purine biosynthesis is associated with growth suppression in ZR-75-30 breast cancer cells after silencing of PAICS has not been proven in this study." (PMID 30097015, 2018). "Overall, these results suggest that PAICS is highly expressed in cancer and can be a marker of breast tumor progression and that four enzymes of the purinosome complex, including PAICS, may determine disease outcomes, particularly in patients with ERα+ breast cancer treated with tamoxifen." (PMID 37172090, 2023). "In vivo assay further validated the significance of the miR-4731-5p/PAICS/FAK axis in vivo tumorigenesis and lung metastasis in breast cancer." (PMID 35379785, 2022). "To further validate the effects of the miR-4731-5p/PAICS/p-FAK axis on breast cancer in vivo, we established a nude mouse model of breast cancer xenograft tumor." (PMID 35379785, 2022). "Collectively, our findings indicated that miR-4731-5p inhibited breast cancer cell glycolysis and EMT through the reduction of PAICS-induced phosphorylation of FAK." (PMID 35379785, 2022). "PAICS, an de novo purine biosynthesis enzyme, was overexpressed in lung SQCC, breast cancer, and colorectal cancer cells." (PMID 34439333, 2021). "Lentivirus-based short hairpin RNA targeting PAICS specifically depleted its endogenous expression in ZR-75-30 and MDA-MB-231 breast cancer cells." (PMID 30097015, 2018). "By further analysing above EMT-related RBPs and AS in breast cancer tissues in TCGA, it was found that the expression levels of ADAT2, C2orf15, SRP72, PAICS, RBMS3, APOBEC3G, NOA1, ACO1 and the AS of TNC and COL6A3 were significantly correlated with the prognosis of breast cancer patients." (PMID 38783078, 2024). "PAICS, a key enzyme for de novo purine synthesis, activates the cAmp/PKA signaling pathway, promotes mTOR activity, activates estrogen receptor alpha, and enhances estrogen dependence and tamoxifen resistance in breast cancer." (PMID 39256367, 2024). "As PAICS was highlighted as a potential target gene of miR-4731-5p by initial bioinformatics analysis in our investigation, we speculated that miR-4731-5p might regulate the oncogene PAICS to modulate FAK-driven glycolysis and EMT in breast cancer." (PMID 35379785, 2022). "Moreover, PAICS knockdown led to suppression of glycolysis, EMT, migration, and invasion in breast cancer cells, similar to the effects precipitated by re-expression of miR-4731-5p." (PMID 35379785, 2022). "In addition, we proposed a mechanism wherein miR-4731-5p represses PAICS-dependent phosphorylation of FAK, whereby suppressing the glycolysis of breast cancer cells and reversing EMT process." (PMID 35379785, 2022). "Altogether, these findings indicated that PAICS could reverse the suppressive role of miR-4731-5p in glycolysis, EMT, migration, and invasion of breast cancer cells." (PMID 35379785, 2022). "Subsequently, the expression patterns of miR-4731-5p, PAICS, and FAK in breast cancer tissues and cells were determined, in addition to analyses of their roles in glycometabolism, migration, invasion, epithelial–mesenchymal transition (EMT) analyzed through functional assays." (PMID 35379785, 2022).
breast carcinoma (continued). "Meanwhile, the PAICS gene was recently indicated as a tumor-promotive gene in several human cancers including lung adenocarcinoma (LADC), cervical cancer, and even breast cancer." (PMID 35379785, 2022). "Using lentivirus-based RNA interference (RNAi) we knocked down the endogenous expression of PAICS in the human breast cancer cell lines ZR-75-30 and MDA-MB-231 to explore whether it is involved in breast cancer growth." (PMID 30097015, 2018). "To date, PAICS has been found to affect breast cancer cells growth, however, how it affects cell cycle has not been studied." (PMID 30097015, 2018). "Similarly, our findings validated that miR-4731-5p could reverse the promotive role of PAICS in the malignant progression, including that on glycolysis and EMT induction, which made it plausible to suggest that miR-4731-5p prevented malignant progression of breast cancer via downregulation of PAICS." (PMID 35379785, 2022). "Notably, CDK1, CCNA2, P4HA1, PAICS, and RAD51 showed a CERES score higher than zero in most breast cancer cell lines, indicating that they might not be essential to breast cancer." (PMID 34745136, 2021).
lung carcinoma (11 papers, 2013 to 2024). "High expression of PAICS has also been associated with the poor prognosis of lung cancer and gastric cancer patients." (PMID 35096022, 2021). "We previously reported that PAICS, an enzyme of de novo purine biosynthesis pathway, is associated with lung cancers, prostate adenocarcinomas, and bladder cancers and correlated with upregulated cancer phenotypes, such as proliferation and invasion." (PMID 32218208, 2020). "We investigated the functional significance of the de novo purine biosynthetic pathway genes PPAT and PAICS in lung cancer by loss-of-function analyses of these divergently transcribed and elevated in lung tumors." (PMID 26140362, 2015). "For lung cancer, amplification of PAICS gene and/or overexpression of its protein is significantly associated with poor prognosis of lung adenocarcinoma." (PMID 38463398, 2024). "Hypomethylation of the PAICS gene was reported for lung cancer cells as compared to normal lung cells, possibly contributing to elevated expression." (PMID 37172090, 2023). "PAICS has been localized in lung cancer tissues and shows high expression in tumor tissues as compared to normal tissues." (PMID 35096022, 2021). "A recently developed small-molecule inhibitor (MRT00252040), which targets PAICS, is currently being evaluated for the treatment of ovarian, breast, and lung cancers." (PMID 32218208, 2020). "Meanwhile, PAICS has also been suggested playing vital roles in pathogenesis of other cancers, including bladder cancer and lung cancer." (PMID 32815531, 2020). "We discovered aneuploidy and amplification in the divergently transcribed locus of PPAT and PAICS in a subset of lung adenocarcinoma (∼3% cases) and amplification in H661 lung cancer cell line." (PMID 26140362, 2015). "In this study, we demonstrate that de novo purine biosynthetic pathway enzymes PPAT and PAICS show increased expression in lung cancer and can serve as prognostic markers for patient survival." (PMID 26140362, 2015). "PPAT and PAICS are two such genes that are co-transcribed from locus 4q12 and show genomic amplification in small percentage of lung cancer cases." (PMID 26140362, 2015). "Our data demonstrate that PPAT and PAICS of de novo purine biosynthesis show increased expression in lung cancer compared to normal lung." (PMID 26140362, 2015). "In summary, we identified increased expression of PPAT and PAICS in de novo purine biosynthetic pathway that is potentially useful for lung cancer prognosis." (PMID 26140362, 2015). "We further confirmed the increased expression of divergently transcribed PPAT, PAICS as well as PKM2 expression in lung cancer samples compared to normal samples by next-generation RNA sequencing and quantitative RT-PCR analysis." (PMID 26140362, 2015). "Elevated levels of enzymes involved in the de novo biosynthetic pathway, such as PPAT and PAICS, have been observed in lung cancer and may serve as potential prognostic markers." (PMID 37393565, 2023). "In addition, we showed the critical role of PPAT and PAICS in lung cancer progression both in vitro and in vivo." (PMID 26140362, 2015). "In summary, this study reveals the regulatory mechanisms by which purine biosynthetic pathway enzymes PPAT and PAICS, and pyruvate kinase activity is increased and exposes an existing metabolic vulnerability in lung cancer cells that can be explored for pharmacological intervention." (PMID 26140362, 2015). "In various cancer types, miR-128 functions as a tumor suppressor, targeting epidermal growth factor receptor in lung cancer, polycomb complex protein BMI1 in prostate cancer, PAICS in bladder cancer, and E2F transcription family member E2F3a in glioblastoma." (PMID 32218208, 2020). "These in vitro experiments underscore role of PPAT, PAICS and PKM2 in proliferation and invasion across a cross-section of lung cancers cells." (PMID 26140362, 2015).
lung carcinoma (continued). "Interestingly, we discovered that PPAT and PAICS knockdown substantially diminished pyruvate kinase activity that is comparable to the PKM2 knockdown suggesting that PKM2 could be an important contributor of the pyruvate kinase activity in lung cancer cell lines." (PMID 26140362, 2015). "In addition, Affymetrix microarray analyses showed enhanced expression of PPAT, PAICS and PKM2 in poorly differentiated and stage 3 lung cancers (respectively)." (PMID 26140362, 2015).